SNORA30 (small nucleolar RNA, H/ACA box 30)
Synonyms: ACA30; SNORA30A
Gene: Small nucleolar RNA gene on chromosome 16 (30,710,537 to 30,710,665, forward strand). Ensembl gene ENSG00000206755.
Gene Ontology:
Biological process: RNA processing
Cellular component: nucleolus
Homologues: Orthologues: chimpanzee SNORA30 (98% identical), macaque SNORA30 (94% identical), dog SNORA30 (89% identical), rabbit SNORA30 (88% identical), pig SNORA30 (87% identical). Paralogues in human: SNORA30B (88% identical), SNORA37 (85% identical).